AXL (AXL receptor tyrosine kinase)
Diseases named in the same sentence as AXL in open-access papers (continued):
Sharing a sentence is not in itself a finding about the gene and the disease.
melanoma (continued). "Because we saw a correlation of AXL expression with EDNRA expression in the xenografts, we interrogated publicly available gene expression data, including the TCGA‐melanoma as well as two melanoma cell line datasets." (PMID 28606996, 2017). "Moreover, an independent study utilized RNA-seq analysis to identify factors that protect MITF low melanoma cells from MAPK inhibition and identified AXL as a key RTK upregulated during resistance." (PMID 27834845, 2016). "However, also low MITF/AXL and MITF/EGFR ratios have been suggested to be involved in early resistance to vemurafenib in a subset of melanomas." (PMID 27391157, 2016). "Real time PCR examination of 8 AXL-positive tumors demonstrated that MER and TYRO3 transcripts were barely detectable and immunoblot analysis of representative melanoma cell lines confirmed mutual exclusion of AXL and TYRO3 and frequent co-expression of TYRO3 and MER." (PMID 27102439, 2016). "Regarding resistance to RTK inhibition, we observed that downregulation of IGF-1R and AXL in C8161 melanoma cells expressing ShRUNX2-3 did not result in reduced AKT and ERK phosphorylation but instead increased AKT phosphorylation." (PMID 27102439, 2016). "Indeed, some melanoma cell lines display a ‘neural precursor signature’, which intriguingly contains WNT5A and AXL." (PMID 25818589, 2015). "It is not clear what upregulates AXL or WNT5A expression, but BRAF inhibition in a panel of BRAFmut/AXL+ melanoma cells does not reduce AXL expression." (PMID 25818589, 2015). "Remarkably however, the absence of MITF marks a AXL+/WNT5A+ population of melanoma cells – previously identified as the ‘Hoek's invasive signature cohort’ – that is unresponsive to MAPK pathway inhibitors." (PMID 25818589, 2015). "In this model, expressions of AXL and WNT5A define a distinct MITF‐negative population of melanoma cells, where MITF expression is not linked to BRN2 and the MAPK pathway and cells are MAPK pathway inhibitor unresponsive." (PMID 25818589, 2015). "Silencing CDK6 and FSCN1, but not AXL, significantly reduced melanoma cell proliferation." (PMID 41286309, 2025). "The specific populations studied were selected based on expected intrinsic high tumor expression of AXL (e.g., sarcoma) or hypothesized increased AXL tumor expression upon development of drug resistance in prior lines of therapy (e.g., relapsed/refractory NSCLC and melanoma)." (PMID 41166388, 2025). "Additionally, two cell surface tyrosine kinase receptors constitutively expressed in melanoma cells, AXL (tyrosine-protein kinase receptor UFO) and c-Met (mesenchymal–epithelial transition factor), were also downregulated by either dabrafenib or AZ628 in the parental cell populations." (PMID 39596009, 2024). "We therefore propose that identifying expression levels of MITF/SOX10, AXL/EGFR/ERBB3 prior to initiation of treatment may contribute to predicting treatment response to MAPK inhibitors and perhaps advice on drug combination strategies in melanoma." (PMID 36251678, 2023). "Also AXL, a member of the TAM tyrosine kinase receptor family, plays a central role in the mesenchymal motif by regulating cell proliferation, EMT, migration, and immune responses in melanoma cells." (PMID 37898636, 2023). "Interestingly, the AXL-targeting agent, Enapotamab vedotin (EnaV), which is an antibody-drug conjugate (ADC), was found to stimulate the release of DAMPs in human models of lung cancer and melanoma." (PMID 35572601, 2022). "We then identified that AXL is a key upstream effector of AKT pathway-associated resistance to BRAFi in melanoma with wild-type PTEN26, but not in melanoma with PTEN loss or inactivated PTEN26,27, implicating the existence of a different mechanism of BRAFi resistance in melanoma with impaired PTEN." (PMID 34282258, 2021).
melanoma (continued). "A subset of melanocyte dedifferentiation gene sets, specifically neural crest genes, the melanoma invasion program, and the AXL program, but not markers of melanocyte stem cells, were activated by either TPA-free media or BRAFV600E expression, albeit the activation was more pronounced in the former." (PMID 34812139, 2021). "NFATc2+ melanomas expressed AXL, N-cadherin and ZEB1, but lacked MITF." (PMID 30710146, 2019). "Taking melanoma as an example, some patients with melanoma have been clinically found to have poor outcomes when given BRAF/MEF inhibitors, and further studies have found that the tyrosine kinase receptor AXL is highly expressed on the surface of tumor cells that react poorly to BRAF/MEF inhibitors." (PMID 30849971, 2019). "Interestingly, in our setting, MITF downregulation at late PT was accompanied by increasing AXL expression, suggestive for a role of AXL in melanoma cells proliferation in the absence of MITF." (PMID 29614062, 2018). "Thus, different combinations of therapies should be effective in treating different phases of melanoma, such as the combination of targeted therapies with inhibitors of MITF expression during the initial treatment phase, but with inhibitors of WNT5A/AXL/NF-κB signaling during relapse." (PMID 29881716, 2018). "This study confirmed the negative correlation between MITF and AXL in melanoma cells." (PMID 27102439, 2016). "These subpopulations of ‘MITF‐negative’ cells, which are contained within a subset of melanoma cell populations originally identified by Hoek and colleagues, are characterized by the expression of the non‐canonical Wnt ligand WNT5A and the receptor tyrosine kinase AXL." (PMID 25818589, 2015). "Finally, the upregulation of AXL by SSMC is of particular interest, because AXL belongs to the TAM (Tyro3, AXL, MER) family of receptor tyrosine kinase involved in various cancers, including melanoma." (PMID 24344100, 2013). "However, according to the bioinformatics analysis, among the three TAM RTKs, only TYRO3 is involved in anti-PD-1 resistance, while higher AXL or MERTK expression did not correlate with shorter survival times for melanoma patients who were treated with anti–PD-1." (PMID 35399527, 2022). "Furthermore, since a low MITF/AXL ratio was recognised as a predictor of early resistance, microRNA (miRNA) regulation of MITF expression was also explored as a novel therapeutic target to reverse the resistant phenotype among many other miRNA pathways dysregulated in melanoma." (PMID 36292642, 2022). "In melanoma cells resistant to MAPK inhibitors including BRAFi, a state of low expressions of MITF and SOX10 could induce high levels of tyrosine kinase receptors, such as AXL receptor tyrosine kinase (AXL) and epidermal growth factor receptor (EGFR) that help to maintain the resistance." (PMID 32532957, 2020). "Similarly, in glioma and melanoma, AXL overexpression did not alter proliferation." (PMID 28025482, 2016). "Furthermore, AXL+/WNT5+ melanoma cells, lacking MITF expression, are highly invasive." (PMID 25818589, 2015). "AXL, CDK6, and Fascin did not specifically correlate with the stage of the melanomas from which these cell lines were derived, while MITF expression negatively correlated with FRA1 and its targets." (PMID 41286309, 2025). "RIPK1 is described as an oncogenic driver in melanoma due to its scaffold function independent of the kinase function, while RIPK3 expression apparently is suppressed by the BRAF and AXL oncogenes." (PMID 35422482, 2022). "Like the proinvasive receptor tyrosine kinase AXL, EGFR is expressed in dedifferentiated melanoma cells in a negative correlation with the melanocytic lineage factor MITF." (PMID 33916908, 2021). "Although we did not perform statistical analyses on the three transitory melanoma cell lines, TNFα clearly reduced both MITF and Melan A levels and concurrently increased NGFR and AXL expression in this melanoma subtype." (PMID 34073253, 2021).
melanoma (continued). "Although Müller and colleagues reported an inverse correlation between AXL and MITF levels in drug-resistant melanoma, drug resistance is not exclusively determined by AXLhigh/MITFlow phenotype." (PMID 33800547, 2021). "As revealed by qRT-PCR analysis, A549 lung adenocarcinoma, MA-2 and MC-1 melanoma, MDAMB231 and 4175-TGL breast cancer cells express AXL (AXL+), while SKBR3 breast tumor cells do not (AXL-)." (PMID 32174798, 2020). "In this regard, it has been unclear how melanoma cells with low MITF survive and proliferate in vivo, the majority of which apparently do not exhibit elevated AXL protein expression." (PMID 30651597, 2019). "Ectopic expression of TYRO3 in the MCF10A breast cancer cell line induced AKT phosphorylation in the presence of GAS6 and treatment with GAS6 promoted AKT phosphorylation in the MDA-MB435 melanoma cell line, which expresses TYRO3 but not MERTK or AXL." (PMID 30501104, 2018). "Importantly, inhibition of AXL with the R428 small molecule (Bergen Bio, Bergen, Norway) is sufficient to sensitize melanoma cells to MAPK inhibition, suggesting that AXL inhibition may be an effective strategy to prevent and inhibit MAPK resistance in patients with melanoma." (PMID 27834845, 2016). "Importantly, MMDR is described in three different BRAF mutant melanoma cells, regardless of their transcriptional phenotypic MITF/AXL signature." (PMID 34957688, 2022). "Interestingly, when we examined the relationship between MITF/AXL ratio and IL1B using 18 human melanoma cells without drug treatment, we found a strong inverse correlation between the MITF/AXL ratio and IL1B gene expression." (PMID 33396632, 2020). "In this context, it is striking that ~14% of melanomas stain positive for MITF and AXL, but it is not clear, whether in these tumours, cells have undergone partial switching." (PMID 25818589, 2015). "Pre- or post-therapy melanoma samples from the other two unresponsive patients (P2 and P5) and from the two responsive ones (P1 and P4), instead, did not have detectable staining of EGFR or AXL." (PMID 25742786, 2015). "The gene expression profile of AXL, which is at the top of the list of migration-related gene, was remarkably similar to that of the mesenchymal marker genes VIM and SNAI2 (Slug), with some exceptions, most notably by melanoma lines that strongly expressed VIM and SNAI2, but not AXL." (PMID 22570691, 2012). "Conversely, dedifferentiated melanoma cells are not very proliferative, but particularly invasive, and show low expression of MITF and high expression of mesenchymal, invasive, extracellular matrix (ECM), and resistance markers such as the receptor tyrosine kinase (RTK) AXL." (PMID 36774337, 2023). "Furthermore, enforced expression of recombinant IL32α, -β, or -γ in M397 did not impact expression of melanoma differentiation genes MITF, AXL, NGFR or MLANA, strongly suggesting that IL32 is not a causal or upstream event in the melanoma dedifferentiation process." (PMID 30953519, 2019). "However, proliferative and invasive phenotypes are not a characteristic of all melanoma cells within a single tumor, and a spectrum of MITF expressing and AXL expressing cells exist in any single tumor that can be manipulated through treatment with RAF and MEK inhibitors." (PMID 29383127, 2017). "While MITF expression does not seem to be relevant in this melanoma cell population, both WNT5A and AXL expressions correlate with clinical response and therapy resistance, suggesting that assessing the AXL/WNT5A expression status could be used as prognostic and/or predictive marker." (PMID 25818589, 2015).
lung cancer (138 papers, 2010 to 2026). A malignant neoplasm involving the lung. "We treated the HER2‐amplified SKBR3 breast cancer line with lapatinib and the EGFR‐mutated HCC827 lung cancer line with erlotinib and combined those treatments with AXL inhibitors." (PMID 39395205, 2025). "Recently, a series of studies linked AXL to several receptor tyrosine kinase inhibitors including EGFR inhibitors in lung cancer, head and neck cancer and colorectal cancer, HER2 inhibitors in breast cancer, and FLT3 inhibitors in AML." (PMID 36835239, 2023). "High invasiveness of CD133 (+) colonies in lung cancer PDO are also associated with activation of AXL, TGFβ, and JAK1, proofed by effective treatment of AXL inhibitor TP-0903 and JAK inhibitor Ruxolitinib." (PMID 36696006, 2023). "Overexpression of AXL has been found in EGFR-mutated lung cancer models that acquired resistance to the first-, second- or third-generation TKIs." (PMID 37894376, 2023). "In recent work, we found an association between lower amounts of MHC I and high AXL expression in lung carcinoma cell clones." (PMID 35572601, 2022). "JNK1 overexpression significantly decreased the expression of AXL and caused G1 arrest and apoptosis in lung cancer cells." (PMID 33546236, 2021). "In contrast, in EGFR-mutated lung cancer cell lines expressing low levels of AXL (HCC827, HCC4006, and H3255 cells), EGFR TKI tolerance was mediated by an insulin-like growth factor-1 receptor (IGF-1R) through the induction of its transcription factor FOXA1." (PMID 34202566, 2021). "We previously reported that the susceptibility of EGFR- mutated lung cancer cells to EGFR-TKIs including osimertinib inversely correlated with the expression of AXL in tumor cells." (PMID 32929081, 2020). "In conclusion, we uncovered the mechanism by which AXL-low-expressing EGFR-mutated lung cancer cells demonstrated tolerance to osimertinib." (PMID 32929081, 2020). "On the other hand, we demonstrated that in AXL-low-expressing EGFR-mutated lung cancer cells, osimertinib exposure increased protein expression and phosphorylation of IGF-1R and thereby restored the survival signal mainly via Gab1 and IRS1 to emerge tolerant." (PMID 32929081, 2020). "For instance, inhibition of ubiquitination and increased protein stability has been reported associated with AXL cell surface accumulation in response to AXL inhibition in breast and lung cancer cells." (PMID 31917795, 2020). "In AXL-high-expressing EGFR-mutated lung cancer cells, osimertinib exposure inhibits ERK phosphorylation and thereby decreases the expression of SPRY4 maintained by ERK-mediated MAPK signal." (PMID 32929081, 2020). "For example, cisplatin treatment induces AXL and GAS6 expression by cancer associated fibroblasts to promote the migration of AXL-expressing lung cancer cells." (PMID 33014869, 2020). "Considering these issues, we chose the transient combination of the IGF-1R inhibitor with osimertinib, demonstrating a favorable efficacy and safety in the CDXs and PDX models of AXL-low-expressing EGFR-mutated lung cancer." (PMID 32929081, 2020). "AXL was highly expressed in clinical specimens of EGFR-mutated lung cancers and its high expression was associated with a low response rate to EGFR-TKI." (PMID 30651547, 2019). "AXL inhibition reduced the viability of EGFR-mutated lung cancer cells overexpressing AXL that were exposed to osimertinib." (PMID 30651547, 2019). "Our findings demonstrated a pivotal role for AXL in the intrinsic resistance of EGFR-mutated lung cancer to osimertinib and the emergence of osimertinib-tolerant cells." (PMID 30651547, 2019).
lung cancer (continued). "High expression of the AXL protein in tumors is reported to be associated with poor prognosis in patients with several types of cancer including glioblastoma, breast cancer, lung cancer, and acute myeloid leukemia." (PMID 30651547, 2019). "In this study, we examined the potential relationship between cell stiffness and motility with AXL in the malignant progression of lung cancer and the underlying mechanism." (PMID 29259259, 2017). "AXL activation has been recently reported to confer acquired resistance to EGFR-TKIs in lung cancers with EGFR mutations." (PMID 27100677, 2016). "AXL activation is associated with drug resistance in lung cancer cells." (PMID 38499647, 2024). "On the other hand, previous studies have reported that enhanced AXL expression is often associated with acquired resistance to osimertinib in lung cancer cells, and also that enhanced expression of both AXL and CDCP1 is associated with poor outcomes of patients with NSCLC23." (PMID 35643725, 2022). "AXL is an angiogenetic marker and associated with the invasion and progression of lung cancer." (PMID 32872195, 2020). "Together with findings that osimertinib increased the IGF-1R protein level, these results strongly suggest that an increased amount of IGF-1R, which maintains the association with EGFR and Gab1, may restore survival signals in AXL-low-expressing EGFR-mutated lung cancer cells exposed to osimertinib." (PMID 32929081, 2020). "It has been shown that the downregulation of AXL in lung cancer cells resistant to EGFR TKIs reverts the EMT process and sensitizes the cells to tyrosine kinase inhibitors." (PMID 40243603, 2025). "Of note, increased expression of AXL and its ligand GAS6 has been detected in samples from patients with EGFR-mutated lung cancer who acquired resistance to EGFR TKIs." (PMID 40243603, 2025). "Enapotamab vedotin (EnaV), a novel anti-AXL human IgG1 and monomethyl auristatin E antibody–drug conjugate, demonstrated antitumor activity in preclinical models, including non–small cell lung cancer (NSCLC)." (PMID 41166388, 2025). "A previous study by Cho and colleagues demonstrated that PTBP1 contributes to AXL mRNA degradation by targeting its 5’UTR in lung cancer cells." (PMID 41313521, 2025). "Their study demonstrated that adaptive activation of AXL engages endogenous hypermutators in lung cancer cells treated with EGFR inhibitors." (PMID 38338651, 2024). "These inhibitors are being studied for lung cancer in which AXL tends to be overexpressed, a disease mainly treated with platinum‐based compounds." (PMID 38501485, 2024). "In lung cancer cells harboring EGFR-sensitive mutations, YAP activation leads to the upregulation and activation of the tyrosine kinase receptor AXL." (PMID 38499647, 2024). "This indicates that mesenchymal markers must be incorporated for better detection of AXL+ CTCs in lung cancer." (PMID 38132919, 2023). "According to our previous study, AXL overexpression in lung cancer cell lines results in elevations in cell invasiveness and drug resistance." (PMID 37834326, 2023). "Epithelial–mesenchymal transition (EMT) and AXL overexpression are often observed in EGFR–TKI–resistant lung cancers." (PMID 37834326, 2023). "AXL is overexpressed in several types of tumors, including lung cancer, and this feature is correlated with poor prognosis." (PMID 37894376, 2023). "In lung cancer patients, the average expression of AXL, BSG, KEEMEN1, and TFRC was very low compared to controls." (PMID 38034398, 2023). "In the present study, we examined the expression of SARS-CoV-2 entry genes, including ACE2, TMPRSS2, CTSL, and AXL in primary human airway epithelial cells isolated from 11 lung cancer patients." (PMID 36148455, 2022). "Among the available lung cancer cell lines, AXL was detected at high levels by WB and flow cytometry in A549 and HCC827-ER3 cells (erlotinib-resistant cell line, according to previous reports) but not in HCC827 cells." (PMID 36261437, 2022).